CD4 (CD4 molecule)
Diseases named in the same sentence as CD4 in open-access papers (continued):
Sharing a sentence is not in itself a finding about the gene and the disease.
Arthritis (continued). "Cell transfer of CD4+ T cells from Il17a−/− SKG mice into T cell-deficient mice completely failed to induce arthritis." (PMID 31497022, 2019). "DQ8 Tg mice with deleted CD4 did not develop arthritis, while CD8 deficient DQ8 Tg mice developed severe CIA along with increased autoantibody levels, suggesting that CD4+ T cells, but not CD8+ T cells are indispensable for initiation of CIA." (PMID 30837986, 2019). "We first detected the effects of BANK1-regulated CIA-B cells (B cells from CIA mice with established arthritis) on CD4+ T cells isolated from DBA1/J mice in the presence of the specific CII antigen, which stimulates an antigen-specific reaction, to determine the function of these cells." (PMID 29370826, 2018). "Moreover, the numbers of CD4+/pSTAT3+ (both Ser727 and Tyr705) and CD4+/Src+ splenic T-cells were significantly decreased by kaempferol treatment compared with vehicle-treated arthritis mice." (PMID 29540697, 2018). "Comparing the result of the adoptive cell transfer experiment and flow cytometry analysis of the lymph node cells, the activation and proliferation of T cells largely correlate to the arthritogenicity of the CD4+ T cells, i.e. more activated and proliferative T cells transfer more severe arthritis." (PMID 29118363, 2017). "Furthermore, another clinical trial of this vaccine demonstrated induction of a transient arthritis and dense CD4+ T lymphocytic vasculitis suggesting a pathophysiological role of vaccine-induced T lymphocytes." (PMID 28542576, 2017). "Instead, the adoptive transfer of CD4 T cells that were reactive to RPL23A could induce arthritis, which suggests the direct arthritogenic effect of CD4 T cells." (PMID 28753982, 2017). "Although the overexpression of IL-1 could lead to the activation and proliferation of synoviocytes in an autocrine or paracrine manner, arthritis in this animal model was dependent on CD4 T cells." (PMID 28753982, 2017). "The results corroborate our previous findings, using the same fusion protein approach, in the collagen-induced arthritis model showing dramatic suppressive effects on Th1 and Th17 autoaggressive CD4 T cells and upregulated regulatory T cell activities with enhanced IL10 production." (PMID 28959261, 2017). "However, the absence of OX40 markedly reduced the survival of memory T cells, and late arthritis development was alleviated in the mice that received transfers with CD4+CD28+OX40− T cells." (PMID 28320444, 2017). "Because FTY720 has a strong effect on CD4+ T-cell recirculation, and because collagen-induced arthritis is mediated by CII-specific CD4+ T cells, we investigated how FTY720 affected the development of the CD4+ CII-specific autoimmune T-cell response in the DR1 Tg mice." (PMID 26757712, 2016). "The recognition of the role of IL-17/IL-23 axis and other cytokines, revolutionized studies on the immunopathogenesis of RA and changed the classical concepts of the CD4+ Th1/Th2 paradigm as the main source of cytokine-mediated events during the course of arthritis." (PMID 27802332, 2016). "Treatment of C3H mice with anti-CD4-depleting antibody increased arthritis severity and treatment with anti-CD8-depleting antibody decreased arthritis severity, suggesting T cell responses could mediate Lyme disease pathogenesis." (PMID 27857714, 2016). "Consistent with that hypothesis, Cd4-/- mice are protected from CHIKV-induced arthritis/swelling, suggesting that CD4+ T cells may have a pathogenic role in acute CHIKV disease." (PMID 26436766, 2015). "However, abatacept reduced disease progression and activity in the absence of CD4+ T cells in the CIA mouse model, indicating that abatacept can exert its action in established arthritis independently of its effects on CD4+ T cell activation." (PMID 26290328, 2015). "Furthermore, upon adoptive transfer, only a mixture of γδ T and CD4+ T cells induced arthritis in scid/scid mice." (PMID 26108163, 2015).
Arthritis (continued). "Therefore, our results show that CD4+ T cells direct the tissue specificity of inflammation, and γδ17 cell-derived IL-17 elicits local inflammation and arthritis in Il1rn−/− mice." (PMID 26108163, 2015). "Furthermore, Padi4 KO TNF alpha transgenic (Tg) mice had milder arthritis and less activated CD4+ T cells and some ACPAs than WT–TNF alpha Tg mice." (PMID 26293116, 2015). "In this model, spontaneous arthritis could be prevented by inhibiting LIP of autoreactive CD4+ T cells." (PMID 24586733, 2014). "However, there is increased expression of this receptor subunit in splenic CD4+ cells after onset of arthritis." (PMID 24676270, 2014). "Local re-injection into the knee joint induces a mainly CD4+ T cell-mediated arthritis." (PMID 24491163, 2014). "Further there is induction of IL-22R1 on CD4+ cells during arthritis." (PMID 24676270, 2014). "IL-22R1 is upregulated on CD4+T cells during arthritis and regulates IFN-γ in T cells." (PMID 24676270, 2014). "Similarly, in KBxN mice, iNKT cells activated by α-galactosylceramide (α-GalCer) suppressed glucose-6-phosphate isomerase (GPI) peptide-induced arthritis by suppression of GPI-specific CD4+ T cells." (PMID 24286535, 2013). "An earlier macrophage-derived, and stronger activation of the antiinflammatory cytokine transforming growth factor beta (TGF-β) was observed in IFN-α-treated animals, combined with an increase in CD4+ T cells producing TGF-β when arthritis was triggered by mBSA (day 21)." (PMID 24286140, 2013). "The exacerbation of arthritis by anti-TIM-2 mAbs might result from modulation of CII-specific CD4 T cell responses." (PMID 21426565, 2011). "The transfer of exogenous CD4+CD25+ T cells or Foxp3+-transduced CD4+ cells from healthy mice into pre-arthritic mice inhibits the development of arthritis, suggesting a regulatory role for Treg cells in the development of arthritis." (PMID 21483764, 2011). "Moreover, treated mice were protected from the induction of arthritis up to 60 days following anti-CD4 treatment, while remaining able to mount CD4-dependent immune responses to unrelated antigens." (PMID 20479941, 2010). "Indeed, in arthritis-resistant young mice, upon repeated PG injections, there was a Treg expansion, while in older mice the balance of regulatory/activated CD4+ cells shifted in favor of activated cells." (PMID 19519881, 2009). "Since administration of anti-CD4 monoclonal Abs with immunization prevents the development of arthritis and completely inhibits the production of anti-mGPI Abs in GPI-induced arthritis, mGPI is considered a thymus-dependent antigen to the humoral immune response." (PMID 19900268, 2009). "In addition, the transfer of hIL-32β-producing CD4+ T cells significantly exacerbated collagen-induced arthritis, and a TNFα blockade cancelled the exacerbating effects of hIL-32β." (PMID 17078892, 2006). "In this way, hIL-32β produced by CD4+ T cells exacerbated arthritis in the mouse model." (PMID 17078892, 2006). "Furthermore, hIL-32β-transduced CD4+ T cells showed marked exacerbation of collagen-induced arthritis, an effect that was, in part, cancelled by TNFα blockade." (PMID 17078892, 2006). "In the present study we investigated whether CD134 can be used as a (transient) marker for targeting auto-aggressive CD4+ T cells in actively induced experimental arthritis." (PMID 15899047, 2005). "Here, we investigated whether CD134 can be used as a target for specific drug delivery to activated auto-aggressive CD4+ T cells in arthritis." (PMID 15899047, 2005). "Thus, CD134 can be used as a marker for auto-aggressive CD4+ T cells early in arthritis, and specific liposomal targeting of drugs to these cells via CD134 can be employed to downregulate disease development." (PMID 15899047, 2005).
Arthritis (continued). "Disease-associated HLA-DR alleles, particularly those with the “shaped epitope”, may present arthritis-related peptides, such as those modified by citrullination, leading to the stimulation and expansion of autoantigen-specific CD4+ T cells in the joints and lymph nodes." (PMID 40725063, 2025). "Furthermore, hematogenous spread of nonviable bacterial DNA carried by neutrophils and proinflammatory macrophages from the gut to spleen, bone marrow, and entheses promotes CD4+ Th17 expansion with reduced regulation, joint T cell infiltration, and severe arthritis." (PMID 40762957, 2025). "Given that IL-17-expressing CD4+ T helper 17 (Th17) cells and FOXP3+CD4+ regulatory T (Treg) cells play critical roles in the pathogenesis of both periodontitis and arthritis, we examined whether the R878H mutation affects the differentiation of naive T cells to Th17 or Tregs." (PMID 38838669, 2024). "Furthermore, while our study primarily focused on the effects of eEF2K on CD4+ T cells and arthritis, it’s important to consider that other immune cell types may potentially impact the severity of arthritis as well." (PMID 37875468, 2023). "It was proved, that under arthritis conditions CD4+CD25loFoxp3+ cells may lose Foxp3 expression and undergo trans-differentiation into Th17 cells, that accumulate in inflamed joints and participate in the pathogenesis of autoimmune arthritis which was shown on mice and human cells." (PMID 32111105, 2020). "Given that CD4+ T cells from LNs of pristane-injected rats were able to induce and sustain arthritis in lymphopenic recipients for well over 100 days, we decided to revisit the question of whether T cells were critical for the perpetuation of chronic arthritis in PIA." (PMID 32345366, 2020). "Interestingly, while γδ T cells did not affect the disease severity, WT CD4+CCR6+ T cells were able to induce arthritis in IL‐23R deficient mice." (PMID 31778214, 2020). "The apoptosis resistance observed in these CD4+ T cells could be reversed with the inhibition of autophagy, leading to the amelioration of symptoms in the collagen induced mouse model of arthritis, thus the authors draw attention to autophagy as a promising therapeutic target in RA." (PMID 31137740, 2019). "Moreover, although other cell types (e.g. ILC3 and γδ T cells) are also sources of IL-17 during inflammatory process, our data from adoptive transfer experiments suggest that CD4 T cells are the main target responsible for arthritis aggravation induced by AhR activation." (PMID 29884199, 2018). "SKG arthritis is dependent on Th17, because SKG CD4 T cells that were deficient in IL-17 failed to induce arthritis upon adoptive transfer into RAG2-deficient mice, while the induction of arthritis was accelerated by the transfer of IFN-γ-deficient CD4 T cells." (PMID 28753982, 2017). "CD4 T cells that infiltrated the joints in K/BxN mice secreted IL-17, and the deficiency of IL-17 or IL-23 considerably suppressed the development of K/BxN arthritis but not K/BxN serum-transfer arthritis." (PMID 28753982, 2017). "It will be interesting to further investigate whether LS-102, in addition to its effects on inducing synovial fibroblast apoptosis, suppresses T-cell activation and CD4 T-cell differentiation into Th1 and Th17 in mice during collagen-induced arthritis as well as MOG-induced EAE." (PMID 27417417, 2016). "In this study we analysed the peripheral blood components, i.e. CD14+ monocytes, CD4+, CD8+ and CD56+T lymphocytes (CD3+), CD80+, C-X-C chemokine receptor 3 (CXCR3)+, CD27+ B lymphocytes (CD19+) and CD16+CD56+CD3− NK cells, for their association with arthritis development." (PMID 27629388, 2016). "Herein, toward the classical type II collagen-induced arthritis in rats, the combination treatment of microfracture and in situ transplantation of thermogel-encapsulated BMMSCs was verified to obviously down-regulate the ratio of CD4+ to CD8+ T lymphocytes in peripheral blood." (PMID 25774788, 2015).
Arthritis (continued). "In addition, development of DTH arthritis was dependent on CD4+ T cells." (PMID 22676339, 2012). "Our previous studies demonstrated that immunization using GPI peptide induced IL-17-producing CD4+ T cells while blockade of IL-17 resulted in amelioration of arthritis, suggesting that IL-17-producing CD4+ T cells play a pathogenic role in GPI peptide-induced arthritis." (PMID 23251456, 2012). "Therefore, the development of arthritis in this murine model may be attributed to the combined effects of IL-17 production and a correspondingly low presence of CD4+CD25+ T lymphocytes." (PMID 22461836, 2012). "Finally, since CD4+IFN-γ+ cells were lower in the inflamed joints of IL-23p19-deficient mice, we confirmed the importance of the IL-23/IL-17 axis using IL-17RA deficient mice showing a similar arthritis expression as IL-23p19KO mice." (PMID 20017902, 2009). "Interactions between IL-18 and STAT3 have been shown in a spontaneous arthritis model, where the activation of STAT3 mediated IL-23-induced IL-17A production from CD4+ T cells." (PMID 40777291, 2025). "Along with an improvement in arthritis activity, the proportion of CX3CR1+CD4+ T cells decreased 24 weeks after treatment initiation." (PMID 39910629, 2025). "IL-17+ CD4+ T cells in SF were significantly enriched in the combined ICI arthritis group compared with the PD-1 inhibitor arthritis group (% within CD4+ T cells; PD-1 inhibitor arthritis vs. combined ICI arthritis; 1.52 ± 1.49 vs. 3.42 ± 0.89; P = 0.03)." (PMID 35413951, 2022). "In PB, key cytokine production profiles of CD4+ and CD8+ T cells were similar between the PD-1 inhibitor arthritis and combined ICI arthritis groups." (PMID 35413951, 2022). "We found that C21 raises the numbers of CD4+CD25+FoxP3+ T cells in CIA, a fact that likely contributed to the improvement of arthritis." (PMID 35874732, 2022). "In a rat arthritis model, HSP60 administration showed increased number of Treg cells (CD4+, FoxP3+) in the joint‐draining lymph nodes and improved arthritis symptoms." (PMID 35928554, 2022). "The adoptive transfer of CD4+CD25+ cells significantly reduced arthritis symptoms in CII-immunized mice, while depletion of CD4+CD25+ T regulatory cells aggravated the clinical symptoms in murine CIA." (PMID 35874732, 2022). "Cpd43 was able to reduce arthritis severity in both models: in CIA, Cpd43 decreased CD4 T cell proliferation and survival; in AIA, it increased CD4 T cell apoptosis." (PMID 34220836, 2021). "Because IL-23 induces TNF expression and TNF transgenic mice developed chronic arthritis, these investigators attempted to identify the mechanism for IL-23-induced arthritis with regards to IL-17A, TNF, and CD4+ T cells." (PMID 34067675, 2021). "The expression of Gsdmd in neutrophils and monocytes was higher in comparison to CD4+ T cells and FLSs, indicating the possible relevance of Gsdmd in these myeloid cells to the pathophysiology of SKG arthritis." (PMID 34548542, 2021). "Next, we similarly investigated a role of Ripk3 in CD4+ T cell homeostasis and the SKG arthritis model." (PMID 34548542, 2021). "Active SLE patients with arthritis showed higher OAS2 and OAS3 expression in PBMCs and CD19+ B cells and OAS2 expression in CD4+ T cells (P<0.05)." (PMID 32321151, 2020). "In this study, we showed that continuous delivery of HSP65 in the gut mucosa by L. lactis is a potent tolerogenic stimulus inducing regulatory CD4+LAP+ T cells that prevented collagen-induced and methylated bovine serum albumin-induced arthritis in mice." (PMID 33072101, 2020). "Next, we cotransferred cTregs from either Ptpn2-haploinsufficient or WT CD45.2-marked FoxP3EGFP SKG mice in combination with CD4+ effector T cells isolated from CD45.1-marked WT SKG mice and evaluated the development of arthritis after mannan injection." (PMID 33055428, 2020).
Arthritis (continued). "The frequencies of CD4+CD25+FoxP3+ Tregs in blood, spleen and lymph nodes of mice with S. aureus arthritis, from day 3 to 14 after bacterial inoculation, were higher than those in healthy control mice." (PMID 32111171, 2020). "There was no other difference between Ptpn2+/– and WT mice in total and CD4+ T cells, cTh17 cells, total cTregs, or RORγt-expressing cTregs in early or late DSS-induced arthritis." (PMID 33055428, 2020). "On the other hand, in the CD4+ population, the proportion of CCR7-CD62L- effector memory T cells were increased, but CCR7+CD62L+ central memory T cells were decreased after arthritis improvement in BD patients." (PMID 31614573, 2019). "Chronic depletion of CD4 T cells by anti-CD4 antibody in MRL/lpr mice reduced inflammation, arthritis, nephritis, and dsDNA antibodies." (PMID 31998318, 2019). "In summary, combined treatment with rapamycin and DON additively ameliorated arthritis in SKG mice, mainly by suppressing CD4+ T cell proliferation and Th17 differentiation." (PMID 31011190, 2019). "With the same tendency, in BD patients with arthritis, CCR7+, CD4+CCR7+, and CD8+CCR7+ cell frequencies in whole cells were decreased after improvement." (PMID 31614573, 2019). "As previously shown, T2-MZP Bregs suppressed arthritis and reduced the frequency and absolute number of IFN-γ+ and IL-17+CD4+ T cells in WT mice; however, WT T2-MZP Bregs were unable to convey the same suppressive effect in iNKT cell-deficient mice." (PMID 29449556, 2018). "To confirm a suppressive effect of iNKT cells on arthritis pathogenesis, we transferred CD4+ SKG T cells alone or in combination with SKG iNKT cells to BALB/c Rag2−/− mice and induced arthritis by mannan injection 1 week after cell transfer." (PMID 29980684, 2018). "CD4+ T cells are considered one of the major sources of inflammatory cytokines, especially of soluble RANKL, in arthritis." (PMID 28724396, 2017). "Although CD4 T cells were dispensable to arthritis induced by the injection of anti-GPI antibody (K/BxN serum transfer arthritis), autoreactive KRN CD4 T cells were required for the initiation of arthritis in K/BxN mice." (PMID 28753982, 2017). "Probably owing to natural killer cell or chemokine receptors expressed on CD4+CD28− T cells, mice that received transfers with CD4+CD28−OX40− T cells exhibited deteriorated arthritis progression, especially in early arthritis." (PMID 28320444, 2017). "IL administration of eASCs attenuated the severity and progression of arthritis, reduced bone destruction and increased the levels of regulatory T cells (CD25+Foxp3+CD4+ cells) and Tr1 cells (IL10+CD4+), in spleen and draining lymph nodes." (PMID 28484460, 2017). "Meanwhile, arthritis onset and scores in CIA mice that received transfer with CD4+CD28−OX40− T cells also showed a significant difference from those in control CIA mice (6.57 ± 2.47 vs 3.48 ± 2.12, P < 0.001)." (PMID 28320444, 2017). "For CD4+CD28−OX40− T cells, although early Th1 response aggravated arthritic development in an OX40-independent way, progression faded in late-phase arthritis." (PMID 28320444, 2017). "A77 1726 treatment in arthritis mice exhibited attenuated expressions of STAT3 activity (both pSTATTyr705 and pSTAT3Ser727) in CD4+ T cells, whereas pSTAT5 activity in those cells was significantly augmented." (PMID 28193225, 2017). "Arthritic onset in CIA mice that received transfer with CD4+CD28−OX40+ T cells occurred much earlier, and the arthritis scores in these mice were much higher than those in control CIA mice (8.55 ± 3.17 vs 3.48 ± 2.12, P < 0.001)." (PMID 28320444, 2017). "Granzyme A (rather than IFNγ) from differentiated NK cells and CD4 T cells thus appears to be an important driver of CHIKV arthritis, with granzyme A dispensable for control of CHIKV infection." (PMID 28207896, 2017).